CRP (C-reactive protein)
Diseases named in the same sentence as CRP in open-access papers (continued):
Sharing a sentence is not in itself a finding about the gene and the disease.
infection (continued). "Prior studies indicated that CRP could not be used as a marker of infection in burn patients." (PMID 30595763, 2018). "C-reactive protein may be normal in PcP and can therefore not be used to rule out infection." (PMID 30469526, 2018). "However, CRP levels are not a consistent marker of the severity of infection." (PMID 30170455, 2018). "In the absence of infection, the findings indicate both nCRP and mCRP increase NO and iNOS production by monocytes but the stimulation by nCRP is relatively modest compared to that produced by mCRP at CRP concentrations typical of an acute inflammatory response." (PMID 30013561, 2018). "Could markedly deranged values of C-reactive protein and s-albumin, such as found in this study, signal a relatively short remaining survival time in patients with incurable cancer and no clinical signs of ongoing infection?" (PMID 29534089, 2018). "Besides, unlike PCT, the concentration of CRP in G+ bacterial infection,G− bacterial infection, and fungus infection group was different, which means thatphysicians could identify the infection by measuring CRP levels." (PMID 29846409, 2018). "For instance, should deranged CRP and s-alb values in the absence of clinical signs of infection, be interpreted as a sign of short survival and thus play a larger role in clinical decision-making regarding whether or not to continue treatment such as palliative chemotherapy and extensive surgery?" (PMID 29534089, 2018). "Notably, SF has been shown to increase during infection, giving false negative results; this explains why we observed a significant positive correlation between SF concentration and the inflammation biomarkers (CRP and AGP, data not shown)." (PMID 28152069, 2017). "Yet, unlike PCT, peak CRP may help predict infection in the setting of pLT." (PMID 28201980, 2017). "Therefore, CRP does not appear an ideal parameter to detect infection." (PMID 28264059, 2017). "Notably, CRP increases in the end-of-life in cancer patients also in the absence of infections." (PMID 27608043, 2016). "CRP may be more helpful as it is usually not elevated in CGD patients in the absence of infection." (PMID 29376932, 2016). "Furthermore, regarding the conventional indicators of infection such as WBC, body temperature, and CRP, neither the absolute values nor their change from t−1 to t0 could predict infection." (PMID 27597981, 2016). "However, regarding the percentage and delta changes CRP, temperature and WBC counts diagnostic value did not change, while PCT's AUC for both percentage and delta changes had a significantly better performance for predicting infection." (PMID 27597981, 2016). "However, at a CRP threshold of 5 mg/L, no cases of serious infection were missed in either arm." (PMID 27716201, 2016). "Therefore, CRP alone is not a reliable parameter to identify infection in patients with SLE." (PMID 26273660, 2015). "C-reactive protein (CRP) is a sensitive but non-specific systemic marker of inflammation that is produced mainly in the liver in response to cytokines released by phagocytes during infection, trauma, surgery, burns, tissue infarction, advanced cancer, and chronic inflammatory conditions." (PMID 26321888, 2015). "Although the clinical application of procalcitonin (PCT) as an infection marker in patients with impaired renal function (estimated glomerular filtration rate (eGFR) <60 ml/min/1.73 m2) has been increasing recently, it is unclear whether PCT is more accurate than C-reactive protein (CRP)." (PMID 25407928, 2014). "Though not caused by infection, this points to a diverse capacity of CRP and SAA and that there are conditions or diseases for which SAA could have a clinically higher diagnostic or prognostic value than the more frequently used CRP." (PMID 25430894, 2014).
infection (continued). "The CRP is an acute phase protein and is expressed in early stages of infection, acute phase response was higher in post challenge nontreated mice till 72 hrs PC, whereas the CRP was lower in AX treated mice at 48 and 72 hrs PC; it could be due to the anti-inflammatory potential of AX." (PMID 26464919, 2014). "Although the best accuracy of CRP and PCT in patients with renal impairment might be affected by the partial proportional difference of infection severity, we believe that this point did not substantially compromise the aim of this study to compare CRP and PCT as an infection marker." (PMID 25407928, 2014). "However, according to patient interviews, there was no illness, inflammation or infection, injury, or medication use during the study period, which could relate to their particular CRP levels." (PMID 23484158, 2013). "Also, the CRP values do not rise significantly until almost 14-48 hr after the onset of infection." (PMID 23493845, 2012). "CRP was increased but this could be due to any inflammatory process without concomitant infection." (PMID 18505548, 2008). "In conclusion, PCT, CRP, and WBC are not specific for diagnosing infection in the first week after pediatric LT and should be evaluated alongside clinical symptoms, especially changes in body temperature." (PMID 41007066, 2025). "For model 1, PCT, CRP, and WBC alone did not have significant predictive value for postoperative infection (p > 0.05)." (PMID 40373822, 2025). "After treatment, a follow-up CT scan showed no improvement in the inflammatory lesions, and infection indicators remained abnormal: PCT 4.56 ng/ml, CRP 123.25 mg/l, WBC 21.13×109/L, Neutrophils 19.21×109/L." (PMID 40552119, 2025). "These patients often presented with persistent high fever and poor general condition, even when other inflammatory markers (e.g., neutrophil percentage, CRP, LDH) and chest imaging did not indicate severe infection." (PMID 39911585, 2025). "This dynamic inflammatory pattern, although not captured with daily CRP or ferritin values, reinforces the interpretation that the patient’s VBDS course was immune‐mediated rather than solely drug‐ or infection‐driven." (PMID 41425512, 2025). "In contrast, CRP and PCT are not routine laboratory tests and must be specifically ordered when infection is clinically suspected, as they require separate biochemical assays." (PMID 41303127, 2025). "Laboratory examinations showed elevated inflammatory markers (CRP, ESR, IL-6, and Ferritin) but no abnormalities in infection, immune, or tumor markers." (PMID 40917352, 2025). "Changes in CRP and PCT levels can occur after infection and during recovery, but such changes are not exclusively due to the infection itself." (PMID 40471473, 2025). "White cell count, C-reactive protein (CRP), and documented fever were reviewed to rule out infection." (PMID 40951126, 2025). "CRP and PLT are established nonspecific indicators of inflammation and infection, with documented elevations in acute KD cases." (PMID 41169895, 2025). "In most patients who subsequently developed SSI, no secondary increase in CRP was observed on postoperative days (POD) 4 or 5; instead, CRP levels declined despite the later occurrence of infection." (PMID 41226908, 2025). "A statistically significant decline in CRP levels was observed in patients without SSI, whereas no consistent trend was found in those with confirmed infections." (PMID 41226908, 2025). "IL-6 is also highly useful (AUC = 0.89), whereas CRP and PCT levels do not appear to be reliable for the early diagnosis of infection." (PMID 40806991, 2025). "In our patient, persistent elevation of CRP and ESR, combined with nonspecific MRI findings, initially raised concern for occult infection or malignancy." (PMID 41195412, 2025). "Elevated IL-6 and C-reactive protein (CRP) levels were observed in the majority of cases, indicating a systemic inflammatory response even in the absence of overt infection." (PMID 41458669, 2025).
infection (continued). "Also, although patients with diagnosed concomitant infection were excluded from the analysis, we may have not always determined whether CRP elevation reflected a subsequent/new-onset infection or was solely related to the inflammatory response triggered by AMI." (PMID 41227029, 2025). "The immunosuppressive effects of rATG likely contribute to the delayed elevation of these markers, as previous studies have shown that thymoglobulins can induce increases in both CRP and PCT levels, even in the absence of infection." (PMID 40806991, 2025). "Additionally, since CRP is part of a dynamic and continuous inflammatory process, a single CRP measurement, especially at low concentrations, may erroneously classify an infection as viral rather than bacterial, potentially delaying appropriate antibiotic treatment." (PMID 40920832, 2025). "We hypothesized that the magnitude of CRP elevation would be primarily driven by the extent of surgical tissue trauma (with higher peaks in open and extensive surgeries) and not inherently indicative of infection unless the elevated levels persist beyond the immediate postoperative period." (PMID 41153812, 2025). "Levels of CRP, PCT, NC, and NLR were significantly higher in the infection group compared to the non-infection group (P&lt;0.05)." (PMID 41281267, 2025). "In the present case, the absence of systemic inflammatory response (normal CRP, WBC, and procalcitonin levels) strongly suggests that the infection was confined to the sternal site without significant dissemination." (PMID 41157220, 2025). "Third, while CRP, PCT, and WBC count are useful in assessing inflammation and infection, they are not specific to dengue infection." (PMID 40692953, 2025). "We started antifungal treatment with micafungin (150 mg daily) for 2 weeks; however, the patient continued to experience low-grade fever, and infection markers did not significantly improve (WBC 11.48 × 109/L, ESR 108 mm/h, CRP 73 mg/L)." (PMID 40725965, 2025). "It is also important to note that numerous recent studies have shown that CRP and PCT alone or in combination cannot accurately detect infections, regardless of the nature of the patient cohorts." (PMID 40471473, 2025). "Blood tests were negative for infection (WBC 7000/microl, CRP 0.1 mg/L, ESR 2 mm/h, and procalcitonin 0.02 ng/mL), and the patient was empirically treated with amoxicillin clavulanate for 7 days with success." (PMID 41471903, 2025). "A comparison of the culture results revealed that PCT, CRP, and ESR were elevated in both culture-negative and culture-positive cases, which has significant implications for the early diagnosis of infection." (PMID 40458520, 2025). "Unlike the distinct trend observed in median PCT levels between the two groups, the trajectories of median CRP levels and mean WBC counts were similar between patients with and without postoperative infection." (PMID 40373822, 2025). "Laboratory evaluation was unremarkable, apart from a mildly elevated C-reactive protein (CRP), which was measured to assess for systemic inflammation or infection, neither of which was clinically evident." (PMID 40917922, 2025). "Unlike other inflammatory markers, such as CRP, PCT levels rise more rapidly in response to bacterial infections and decline quickly after effective treatment, providing a dynamic measure of infection status." (PMID 40529435, 2025). "The elevated C-reactive protein (CRP) level was attributed to post-MI changes, as there were no clinical signs of infection." (PMID 39590190, 2024). "Regarding the inflammatory markers, patients with high-virulence PJIs had higher CRP (medians: 18.0 vs. 3.8 mg/L; p < 0.001) and ESR levels (medians: 37.0 vs. 25.0 mm/h; p = 0.002) compared to those without infections." (PMID 39203582, 2024). "Common markers of infection in the clinical setting, such as C-reactive protein (CRP) and procalcitonin (PCT), have good negative predictive accuracy within 36 hours of infection." (PMID 39724075, 2024).
infection (continued). "Patients aged >62.5 years, with a CRP level >12.56 mg/L, or a sputum viscosity >III without obvious signs of infection should be treated with antibiotics to improve their short-term prognosis." (PMID 38799157, 2024). "The combination of CRP, ESR, and white blood cell (WBC) counts is useful in predicting the absence of infection after elective surgery." (PMID 39588453, 2024). "Inflammatory parameters indicated an elevated value of 50 mg/L for CRP and 51 mm/H for ESR, but with a negative preoperative synovial fluid culture and no history of infection, the attending doctor inclined towards aseptic one-stage revision." (PMID 39654596, 2024). "Other clinical findings and laboratory values (notably CRP and WBC) were non-predictive of infection." (PMID 38600998, 2024). "This is noteworthy, especially considering that the average C-reactive protein (CRP) levels in the five suspected cases of infection were 1.5 ± 0.5 mg/dL, which falls within normal limits and does not suggest an infection-related inflammatory response." (PMID 39026078, 2024). "CRP levels were numerically but not statistically higher, and serum albumin levels were numerically lower in patients who had a PEG site infection." (PMID 38463403, 2024). "Patients with subsequent infections exhibited significantly elevated levels of fever, PCT, IL-6, and CRP compared to those without infections (P < 0.001)." (PMID 38956649, 2024). "In LBW babies, there is also a lack of molecular reactants such as C-reactive protein (CRP), inhibitor protein, A amyloid protein, and several coagulation proteins, all of which serve to increase resistance to infection." (PMID 38938686, 2024). "Blood tests showed a mildly elevated D-dimer level (1.4 μg/mL), CRP (0.02 mg/dL), and WBC count (4400/μL), with no signs of inflammation or infection." (PMID 39544547, 2024). "To explore the relationship between these pathogens and blood cell and infection indicators, we examined the ANC, ALC, HBG, and CRP levels in infected and non-infected patients for Anelloviridae, Herpesviridae, Flaviviridae, and non-viral pathogens." (PMID 39044261, 2024). "Procalcitonin (PCT) is a host response marker with high specificity for bacterial infections, unlike C-reactive protein (CRP) or white blood cell count (WBC), which represent the traditional methods of detecting inflammation and infection." (PMID 39420348, 2024). "Unlike CRP, PTX3 is generated at the infection site by a variety of cell types, such as monocytes and neutrophils, in response to inflammatory triggers (such as cytokines or microbial moieties)." (PMID 39294659, 2024). "Preoperative blood tests showed that the patient’s white blood cell count and C-reactive protein (CRP) levels were within normal ranges, indicating no signs of infection." (PMID 39659804, 2024). "Blood test results showed a slight elevation in D-dimer (1.7 μg/mL), with normal C-reactive protein (CRP) (0.01 mg/dL) and white blood cell (WBC) count at 8200/μL, indicating no active inflammation or infection." (PMID 39544547, 2024). "No optimal cutoff values were found for ESR or CRP, with the synovial WBC count being the most reliable test for confirming infection control." (PMID 39493345, 2024). "Patients who are >62.5 years of age, have a CRP concentration >12.56 mg/L, or have a sputum viscosity >III without obvious signs of infection should be treated with antibiotics to improve their short-term prognosis." (PMID 38799157, 2024). "No other effects on C-reactive protein (CRP) level, mortality rate, postoperative infections number, vasopressor/inotropic support, ventilation time, renal function, SOFA score, and ICU length of stay were found." (PMID 38792944, 2024). "Elevations in CRP and/or ESR are not conclusive evidence of infection, but they can be helpful in screening and monitoring spinal infections." (PMID 38173524, 2024).
infection (continued). "Fever, tachycardia, and high C-reactive protein levels remained high during the first 3 days after CAR T-cell infusion, even when no infection was documented." (PMID 39070045, 2024). "The marked difference in CRP levels between the MDRO and non-MDRO groups suggests that CRP is potentially a more effective marker of infection severity, especially in MDRO patients." (PMID 39170607, 2024). "Though her white blood cell (WBC) count and c-reactive protein (CRP) were elevated, PCT was normal, with no apparent source of infection, and hence antibiotic differed." (PMID 37581200, 2023). "Using CRP POCT to better discriminate between severe and non-severe infections, complemented with effective patient communication and when applicable delayed prescribing, are part of the solution to improve antibiotic stewardship in primary care." (PMID 37324137, 2023). "Physicians contacted by phone may diagnose an infection and prescribe antibiotic therapy without a clinical examination based on the nurses’ observations, point-of-care investigations such as urinary dipstick and C-reactive protein analysis, or a resident’s previous infection history." (PMID 37760669, 2023). "Patients diagnosed by their clinical team with infection at baseline had significantly increased CRP and WCCs (p < 0.0001) and double the mortality rates (p = 0.001) but similar MELD scores when compared to those not diagnosed with infection." (PMID 36407574, 2023). "The combination of CRP and AGP can help identify individuals with a recent infection who do not yet show clinical symptoms (increased CRP) as well as those recovering from infections (increased AGP with or without increased CRP)." (PMID 38130330, 2023). "The predictive value of CRP and PCT for infection in patients with SLE is not yet clearly established." (PMID 37051301, 2023). "Currently, the diagnosis is based on the measurement of serum C-reactive protein (CRP) levels, which alone is unlikely to aid in early diagnosis of late-onset infection." (PMID 37496672, 2023). "Five animals in Group B (16.7%) had clinical and histologic signs of a foreign-body reaction with significantly elevated CRP and ESR values but no simultaneous presence of infection was identified (p = 0.04)." (PMID 37888163, 2023). "Comparison of biomarker levels by timing of ART-initiation found a difference in pre-infection to post-ART-suppression by ART timing group for IFN-α2a and CRP; CRP increased and IFN-α2a decreased in the deferred-ART but not in the immediate-ART group." (PMID 37461626, 2023). "The purpose of this study is to determine the normal changing pattern of CRP and WBC in the post-operative period in spinal deformity corrective surgery in the absence of infection to serve as a benchmark in detecting early post-operative SSI." (PMID 37872533, 2023). "CRP and WBC counts are often used as nonspecific markers of bacteremia and invasive local infections." (PMID 37510151, 2023). "The increase in CRP and ESR values in infection and foreign-body reaction cases had similar trends and no statistical difference between these two conditions was noticed (p > 0.05 in all time points, Mann–Whitney test)." (PMID 37888163, 2023). "In this type, the specific highly abundant microorganisms were Cutibacterium spp., and the clinical diagnosis of this type was often non-PJI, indicating that the clinical signs of infection in patients with this type (ESR, CRP) were not obvious." (PMID 37349686, 2023). "In contrast, conventional markers of infection and inflammation, such as a total white cell (TWC) and C-reactive protein (CRP), can be nonspecific." (PMID 37583519, 2023). "The advantages of PCT over CRP, WBC, and Neu are that, unlike them, it increases its concentration only in infections of bacterial origin." (PMID 38050495, 2023). "There is an elevation of plasma CRP, interleukin-1 β, interleukin-6, and TNF-α in diabetic individuals without infection." (PMID 37510185, 2023).